IL2 (interleukin 2)
Diseases named in the same sentence as IL2 in open-access papers (continued):
Sharing a sentence is not in itself a finding about the gene and the disease.
vitiligo (27 papers, 2011 to 2026). Generalized well circumscribed patches of leukoderma that are generally distributed over symmetric body locations and is due to autoimmune destruction of melanocytes. "The aim of this exploratory study was to assess REL and IL2 gene expression and evaluate the relationship between the presence of their polymorphisms (rs6545836 and rs2069763) and susceptibility to vitiligo and disease symptoms." (PMID 42278609, 2026). "Several cytokines implicated in vitiligo pathogenesis—including IL-17, IL-2, IL-6, IL-8, TNF-α, and IFN-γ—are regulated, at least in part, by vitamin D and its analogs." (PMID 41157208, 2025). "LEF administration demonstrated significant immunomodulatory capacity, reducing the serum levels of Th1-associated pro-inflammatory cytokines (IFN-γ, TNF-α, IL-2) while upregulating Th2-derived anti-inflammatory mediators (IL-4, IL-10) in vitiligo mice." (PMID 40725033, 2025). "The clinical association between vitiligo and OP is similarly attributed to the shared influence of pro-inflammatory cytokines, such as IL-17, IL-6, and IL-2, which affect bone remodeling." (PMID 39796035, 2024). "The most common irAE to occur following IL-2 therapy was vitiligo (70% of irAEs were associated with IL-2 therapy)." (PMID 36556267, 2022). "Significant differences in IL2 rs2069763 distribution was found between patients and controls (p = 0.0059, χ2 = 7.57, chi-square test; p_adj = 0.02636, Bonferroni correction), with the C allele being more frequent among vitiligo patients and the A allele showing a potential protective effect." (PMID 42278609, 2026). "Studies suggest that vitiligo patients may also have an increased risk of developing celiac disease due to shared autoimmune mechanisms; indeed, celiac disease is characterized by an elevated concentration of IL-2, IL-8, and IL-10." (PMID 40430113, 2025). "The frequency of CD49a+CD103+CD8+ TRM cells secreting Prf1 and GzmB was increased in the vitiligo lesions of patients, suggesting that the production of IL-2 or IL-15 is enriched in the environment of vitiligo areas." (PMID 39193473, 2024). "In the current study, we demonstrated that T-96 interacted with JAK3 in the CD8+ T cell from vitiligo patients, attenuating IL-2-induced JAK3 phosphorylation." (PMID 37403086, 2023). "To check for the possible signs of systemic inflammation, we measured the concentration of inflammation-associated cytokines (TNF-α, IFN-γ, IL-1b, IL-1Ra, IL-2, IL-5, IL-6, CXCL8, CXCL10, G-CSF, and GM-CSF) in the plasma of vitiligo patients." (PMID 30515176, 2018). "IL-2-related irAEs were primarily vitiligo and thyroid dysfunction (70% of IL-2 related irAEs), with limited further impact." (PMID 29254506, 2017). "Another study found that IL-2 and GM-CSF maintenance therapy induced vitiligo in a striking 43% of patients (21 out of 49), who demonstrated significantly enhanced survival as compared with unaffected patients." (PMID 21911918, 2011). "In a large retrospective analysis of 374 metastatic melanoma patients treated with high-dose IL-2, a total of 84 patients (22%) developed treatment-related vitiligo, although in patients with objective clinical responses the incidence of vitiligo was nearly 50%." (PMID 21911918, 2011). "Calcineurin inhibitors are immunomodulators and an off-label treatment for vitiligo functioning via inhibiting the lymphocyte and dendiric cells resident proinflammatory protein (calcineurin) that is responsible for the transcription of interleukin (IL)-2 and tumor necrosis factor-α (TNF-α)." (PMID 38850408, 2024). "In addition, a variety of cytokines secreted by T helper cell subsets- Th1 (IFN-γ, TNF-α, IL-2) and Th2 (IL-4, IL-10, IL-13) not only exacerbate autoimmune responses but also perpetuate the vicious cycle of immune dysfunction, ultimately leading to the clinical manifestations of vitiligo." (PMID 40725033, 2025).
vitiligo (continued). "In vitiligo mice, IFN-γ, TNF-α, and IL-2 levels were significantly elevated compared to normal controls (p < 0.001 for all cytokines)." (PMID 40725033, 2025). "Concurrently, the cytokine profile shift—characterized by reduced IFN-γ, TNF-α, and IL-2, alongside elevated IL-4 and IL-10—suggests that LEF promotes an anti-inflammatory milieu, countering the Th1 axis that drives vitiligo." (PMID 40725033, 2025). "The five key target genes (AKT1, VEGFA, ESR1, IL2, and MPO) identified by the compound–target network were closely related to the pathogenesis and/or treatment of vitiligo." (PMID 38659590, 2024). "One third of the Pmel-1/IL-2 treatment group and all mice in the TBI-treatment groups displayed vitiligo at 50 days post therapy." (PMID 36497152, 2022). "The obtained findings suggest that IL2- and REL-related immune pathways influence vitiligo pathogenesis and clinical heterogeneity; however, these exploratory findings should be interpreted cautiously and require confirmation in studies with greater statistical power." (PMID 42278609, 2026). "The other most frequently reported irAE from IL-2 with or without interferon, specific to patients with mM, is vitiligo, a depigmentation phenomenon that requires no intervention." (PMID 29254506, 2017). "Meanwhile, there is mounting evidence that the immunological milieu of vitiligo is also characterized by cytokines connected to other Th2 cell responses, such as IL-4, IL-5, IL-10, IL-13, and IL-31, rather than just Th1 cells and related cytokines (IFN-γ, TNF-α, and IL-2)." (PMID 38695020, 2024).
dengue (26 papers, 2008 to 2025). "Previously, a low frequency of gamma interferon (IFN-γ)- and interleukin 2 (IL-2)-producing T cells has been linked with clinically manifested forms of dengue, whereas a high frequency of corresponding cells conferred protection from symptomatic dengue." (PMID 37903443, 2023). "Cytokines including TNF- α, IFN- γ, IL-1β, IL-2, IL-6 and IL-10 have been linked to the pathogenesis of other viral hemorrhagic diseases, such as dengue, and Ebola." (PMID 34793450, 2021). "Using an 8-color flow cytometry panel, we then measured the number of CD3+ CD4+ or CD3+ CD8+ T cells producing cytokines that have been implicated in natural dengue disease: IFNγ, TNFα, IL2, and IL10." (PMID 22816004, 2012). "Receiver operating characteristic (ROC) curve analysis revealed that IL-2 has the potential to act as a marker to distinguish dengue from other febrile illnesses and is positively correlated with Th1 cytokines." (PMID 38003826, 2023). "It has been shown that T cells collected from children who developed subclinical secondary infection produced more TNF-α, IFN-γ, and IL-2 after stimulation with dengue antigens than those from children presenting symptomatic secondary DENV infection." (PMID 38003826, 2023). "To understand if our dengue vaccine candidate, DSV4, also induces T cell memory, we did a long-term antigen stimulation of the immunized mice with dengue EDIII 1-4 peptide pool along with IL-2 for ten days." (PMID 36926350, 2023). "We showed that IFN-α, IFN-γ, TNF-α, IL-6, MCP-1, IL-2, IL-4, and IL-10 production was higher in patients with dengue than in those with AFI." (PMID 38003826, 2023). "IL-2 increase can be attributed to serotype-specific dengue protein interaction and/or heterotypic infection, which warrant further research." (PMID 34447698, 2021). "In dengue-infected mice we found increased levels of sIL-2R that peaked on day 8 p.i., similar to the curve observed for IL-2." (PMID 21695193, 2011). "In dengue infection, IL-2 levels were associated with dengue but did not significantly correlate with disease severity." (PMID 41194029, 2025). "Thus, IL-2 secretion is crucial in dengue-infected patients for the differentiation of naïve CD4+ T cells into regulatory CD4+/CD25high/Foxp3+ T cells." (PMID 38003826, 2023). "Conversely, IFN-γ and IL-2 were highly elevated during dengue fever and were low in severe DHF." (PMID 36423184, 2022). "As part of the host immune response, various cytokines, including interleukin (IL)-2, IL-6, tumor necrosis factor (TNF)-α, and interferon (IFN)-γ, contribute to severe dengue." (PMID 38306389, 2024). "Multifunctional CD4+ T cells (predominantly expressing IL-2) were induced by DPIV, with higher frequencies in dengue-primed adults." (PMID 36316335, 2022). "Serum concentrations of IL-2, IL-4, IL-6, IFN-γ, TNF-α, IL-17, and IL-10 were determined in dengue patients at 6 or 7 days of fever onset and were compared with values obtained in a group of healthy controls." (PMID 28827898, 2017). "Several observations suggest a massive T-cell activation during DHF, producing cytokines (interferon γ, interleukin 2, TNF α) and infected cell lysis by CD4+ and CD8+ dengue specific lymphocytes are responsible for plasma leakage." (PMID 25242847, 2014). "We also found that DENV-infected patients had higher levels of IL-2 than AFI patients without dengue, which supports the findings from a previous study." (PMID 38003826, 2023). "However, another study found that IL-2 levels were significantly elevated in severe dengue compared to non-severe cases." (PMID 41194029, 2025). "Our first priority was to compare the levels of IL-1b, IL-2, IL-4, IL-6, IL-8, IL-10, IL-12p70, IL-17A, IL-33, CD14, CD54, CD62E, CD62L, CD62p, CD106, CD121b, CD154, CD178, GM-CSF, IFN-g, MIF, ST2 and TNF in plasma samples of dengue group, OF group and Healthy group." (PMID 33809042, 2021).
dengue (continued). "In summary, we found that patients with severe dengue had lower T cell numbers but that DV-NS3 specific T cells produced high levels of IFNγ but not IL-3, IL-13, IL-2, IL-10 or IL-17." (PMID 23209731, 2012). "We found that whilst patients with severe dengue had lower total T cell numbers, the DV-NS3 specific T cells persisted and produced high levels of IFNγ but not TNFα, IL-3, IL-13, IL-2, IL-10 or IL-17." (PMID 23209731, 2012).
Hepatitis (26 papers, 2012 to 2023). Inflammation of the liver. "It is a common perspective that the progress of hepatitis is associated with a series of proinflammatory cytokines such as IL-2, IL-6, IL-1β and TNF-α." (PMID 24498418, 2014). "Thus, treatment with NAC attenuated the release of ConA-induced hepatitis-associated cytokines, such as IL-2, IL-6, IFN-γ, and TNF-α." (PMID 25821351, 2015). "In acute hepatitis patients, high levels of sIL-2Rα returning to normal during resolution has been suggested to be associated with the diagnosis of inflammation in hepatitis, a process in which interleukin 2 may participate." (PMID 22384080, 2012). "For example, it has been recently shown that group‐1 ILCs regulate T cell‐mediated liver immunopathology induced in hepatitis by controlling local IL‐2 availability." (PMID 36967480, 2023). "Overall, the increasing hepatitis activity during AF was found to be correlated well with the up-regulation of IL-2 (major cytokine activating cytotoxic T cell) and IFN-γ." (PMID 35163330, 2022). "Systemic inflammatory response, including TNF, IL-8, IL-6, and IL-2, contributes to the transition from stable chronic liver disease to HBV-ACLF, which is associated with morbidity and mortality of hepatitis." (PMID 33868273, 2021). "In summary, our data show that sorcin−/− animals display enhanced ConA-induced hepatitis and express more cytokines (IL-2, IL-4, IL-17, and IFN-γ) than the wild-type controls, indicating that sorcin acts as a negative regulator in immune response in vivo." (PMID 28706517, 2017). "Less than 5% of limited irAEs related to IL-2 alone required intervention (i.e. holding IL-2), and these included joint pain, neuropathy, hepatitis." (PMID 29254506, 2017). "Some studies comparing patients with hepatitis B and C showed increased levels of plasma IFN-γ, TNF-α, and IL-2 in patients with hepatitis B14." (PMID 28928388, 2017). "Within the database only two ipilimumab treated patients were reported as having autoimmune toxicity during IL-2 dosing, one with hepatitis and one with myasthenia gravis." (PMID 27660706, 2016). "It is well known that the progression of hepatitis is closely associated with inflammatory factors including TNF-α, IFN-γ, IL-1β, IL-2, IL6 and iNOS." (PMID 27035150, 2016). "A number of proinflammatory cytokines play key roles in the progression of hepatitis, such as IL-2, IFN-γ, and TNF-α." (PMID 25821351, 2015). "We have shown that ethyl pyruvate is able to prevent Con A-induced hepatitis by down-regulating the production of inflammatory cytokines such as IL-2, IL-6, IL-1β and TNF-α." (PMID 24498418, 2014). "Furthermore, we detected pro-inflammatory cytokines TNF, IL-1β, IL-12p70, IFN-γ, IL-6, IL-2, and IL-17A corresponding with ConA-induced hepatitis and found that pro-inflammatory factors all rise at 6 h after ConA injection." (PMID 36248904, 2022). "This may mimic events in vivo in which an inflammatory hepatic cytokine microenvironment, found in hepatitis or cancer, dominated by IL‐1, IL‐2, IL‐6, IL‐12, IL‐15, IL‐18, IFNα, IFNγ, and TNFα/β 38, 39, may lead to the expansion of CD49a+ NK cells." (PMID 28952190, 2018). "A previous study has also shown that IL-2 stimulated the expression of pro-inflammatory cytokines/chemokines from liver nonparenchymal cells, such as T cells, Kupffer cells, and stellate cells, which contributes to liver inflammation." (PMID 28714885, 2017). "Thus, 74 HC with known hepatitis B vaccination status were also analyzed regarding their HBsAg-dependent IFNγ and IL2 release." (PMID 25968473, 2015). "However, it is tempting to speculate that during hepatitis, IL-2 produced by liver-infiltrating T cells might support effector function of hepatic ILC2." (PMID 31974518, 2020). "Natural killer (NK) cells mount an immune response against hepatitis C virus (HCV) infection and can be activated by several cytokines, including interleukin-2 (IL-2), IL-15, and interferon-alpha (IFN-α)." (PMID 35891518, 2022).
Hepatitis (continued). "Apart from our studies and findings, a prior comprehensive review indicated enhanced expression of Th1 phenotypic cytokines (IL-2 and IFN-γ), and high serum levels of IFN-γ inducible chemokines CXCL-9 and CXCL-10 during the process of hepatitis flare." (PMID 35163330, 2022). "The major cytokines involved in hepatitis development are tumor necrosis alpha (TNF-α), interferon gamma (IFN-γ), interleukin-2 (IL-2), and IL-6, of which TNF-α and IFN-γ are the dominant cytokines in irreversible biological damage." (PMID 27035150, 2016). "Proinflammatory cytokines play important roles in hepatitis, including TNF-α, IFN-γ, IL-2, and IL-6." (PMID 25821351, 2015). "TFA-JHDN-5 immunizations induced significantly more hepatitis, serum levels of TFA antibodies, CYP2E1 autoantibodies, and hepatic tissue levels of interleukin (IL)-1β, IL-2, IL-4, IL-5, IL-6, IL-17, interferon (IFN)-γ, and tumor necrosis factor (TNF)-α by 3 weeks." (PMID 30305319, 2018). "In addition, IL-2, IL-6, IL-1β and TNF-α were maximally expressed at 6h, indicating these four cytokines mainly expressed in the early phase of Con A-induced hepatitis." (PMID 24498418, 2014). "We found that A. cantoniensis Hance may enhance the activity of protein kinases, promote the growth of neuronal cells body, and regulate hepatitis related signaling pathways (PI3K-AKt, MAPK, IL-2/IL-6/IL-17 signaling pathway and so on), which can serve as a reference in hepatitis E treatment." (PMID 37035802, 2023). "Additionally, IL-2, IL-6, IFN-γ, and TNF-α expression peaked at 12 h, indicating that these cytokines were most robustly expressed during the early phase of ConA-induced hepatitis." (PMID 25821351, 2015). "In a study on similar populations to those in this study, the postpartum IL-2 level had no variation, but IFN-γ expression was higher in patients with hepatitis flare than in patients without hepatitis flare." (PMID 35493501, 2022).
Hypertension (26 papers, 2014 to 2025). The presence of chronic increased pressure in the systemic arterial system. "The increase of inflammatory cytokines (TNF-α, IL-2, IL-6 and IL-10) in the serum indicates an increase of systemic inflammation and a risk of hypertension for the mercury-exposed population." (PMID 33083327, 2020). "In addition to the already discussed cytokines, IL-2 has been implicated in the development of hypertension in humans and animal models." (PMID 33083327, 2020). "IL-2 is expressed in the syncytiotrophoblast in the human placenta, and it has been shown that in low dosages it normalizes hypertension in a mouse model of placental ischemia." (PMID 38920640, 2024). "We further analyzed the effect of host characteristics (age, sex, smoking status, hypertension, and BMI) on the frequencies of cells producing IL‐2 and IFN‐γ." (PMID 35759229, 2022). "In this study, we investigated the effects of recombinant IL-2 supplementation on PE characteristics such as hypertension and placental and renal mt dysfunction/ROS in RUPP rats." (PMID 34685775, 2021). "Previous studies have shown that IL-2 attenuated progression of hypertension in Dahl S rats, which was accompanied by improvements in renal dysfunction and cardiac hypertrophy." (PMID 34685775, 2021). "The objective of this study was to examine a role for IL-2 in NK cell activation, fetal growth restriction, and hypertension during pregnancy by either infusion of IL-2 or blockade of IL-2 (basiliximab) in normal pregnant (NP) and RUPP rats." (PMID 33407826, 2021). "The levels of TNF-α, IL-2, IL-6 and IL-10 in serum were determined in mercury-exposed participants, suffering from hypertension." (PMID 33083327, 2020). "Subcutaneous injection of IL-2 to young spontaneously hypertensive rats prevented the development of hypertension and normalized blood pressure in salt-sensitive rats with stable hypertension." (PMID 33083327, 2020). "Prolonged mercury exposure increases the risk of developing hypertension through systemic inflammation, as demonstrated by elevated levels of serum inflammatory cytokines TNF-α, IL-2, IL-6 and anti-inflammatory cytokine IL-10." (PMID 33083327, 2020). "Varies cytokines were verified to be involved in fibrosis disease among which IL‐2 was also discovered to function in prolapsed lumbar intervertebral disc and hypertension after glaucoma surgery." (PMID 31608440, 2019). "Patients with a history of hypertension admitted for HD IL-2 therapy should have outpatient antihypertensive medications discontinued immediately prior to IL-2 therapy." (PMID 31546315, 2014). "A study comparing healthy and “almost healthy” persons defined by the lack of exercise or by the use of medications for chronic conditions such as hypertension or osteoarthritis demonstrated lower levels of interleukin 2 and higher levels of interleukin 6 in the latter." (PMID 37780417, 2023). "Other key risk factors for RCC, such as age, smoking, hypertension and BMI, did not have significant effect on the frequencies of cells producing IL‐2 and IFN‐γ." (PMID 35759229, 2022). "Patients who have pre-existing hypertension will need to resume their medications during the week between cycles, usually starting 48 hours after discharge, and they will have to stop these medications within 48 hours prior to their next admission for IL-2." (PMID 31546315, 2014). "We next determined whether administration of IL-2/mAbCD25 complex prevents hypertension in Ang II-infused mice." (PMID 25258681, 2014). "Expansion of T regulatory cells through low-dose IL-2 administration has been shown to lower blood pressure induced via systemic lupus erythematosus in mice; as such, these cells may play a protective role in hypertension." (PMID 36970367, 2023).